INS (insulin)
Diseases named in the same sentence as INS in open-access papers (continued):
Sharing a sentence is not in itself a finding about the gene and the disease.
cancer (continued). "At the organism level, however, “transient” insulin resistance is assumed to be critical in various states such as starvation, infection, trauma, and even cancer to spare glucose for different biosynthetic purposes, such as the production of NADPH nucleotides via the pentose phosphate pathway." (PMID 24175011, 2013). "The treatments analyzed (within 3 years prior to cancer diagnosis) were: insulin glargine, insulin detemir, human insulin, fast-acting insulin and analogues, metformin, sulfonylureas, repaglinide, thiazolidinediones, dipeptidyl peptidase-4 inhibitors, and alpha glucosidase inhibitors." (PMID 24278227, 2013). "Cancer patients have higher insulin levels due to insulin resistance in peripheral tissues." (PMID 24381940, 2013). "The notion that metformin suppresses cancer growth through pathways other than insulin/IGF-1-dependent, indirect drug action has recently been supported by experiments in liver IGF-1-deficient (LID) mice, which had naturally decreased lung tumor multiplicity and burden compared with wild-type mice." (PMID 23986086, 2013). "High levels of endogenous insulin among type-2 diabetics and non-diabetics have also been associated with increased cancer risk in epidemiological studies; with highest risk for liver and pancreatic cancer." (PMID 23837608, 2013). "Regarding the insulin glargine controversy, several methodological flaws and limitations were pointed out in the study that raised the concern, and meta-analysis of trials comparing glargine to other insulin showed neutral effect of glargine on cancer incidence." (PMID 23476808, 2013). "Epidemiological studies probably overestimate the impact of insulin therapy on the incidence of cancer, whereas experimental studies suggest that high doses of insulin could facilitate the onset of at least some forms of malignancies." (PMID 24348585, 2013). "Such a programming effect of breastfeeding on the GH-IGF-axis and/or insulin metabolism could also represent an intermediary factor linking infant feeding to chronic diseases such as cancer and cardiovascular disease." (PMID 24236134, 2013). "Adiponectin may also act directly on cancer cells but may also contribute to ameliorate insulin sensitivity and decrease circulating insulin levels." (PMID 24115945, 2013). "However, studies regarding the relationship between insulin and cancer incidence and mortality in the population from Mainland China are still lacking." (PMID 23308218, 2013). "In addition, 216 (11.0%) prescribed a GLP-1 receptor agonist and 542 (20.4%) an insulin were excluded because of a cancer record, and 148 (7.6%) and 310 (11.5%), respectively, because of glucocorticoid use." (PMID 23330649, 2013). "Here, we attempt to understand the role of insulin in promotion of cancer metabolism." (PMID 23837608, 2013). "The researchers investigated the interactions between DAF-2 (an insulin/IGF-1 homolog associated with aging), CEP-1, and AKT-1 (a protein that belongs to the Protein Kinase B/AKT family of protein kinases that are implicated in a wide range of human cancers)." (PMID 24151577, 2013). "This might indicate that, when patients show a family history for cancer, the use of long-acting insulin in the treatment of DM2 should be reconsidered." (PMID 22554284, 2012). "Suggested links in the biology of DM and cancer include hyperglycemia driving malignant cell growth, the insulin and insulin-like growth factor axis leading to cell survival and mitogenesis, and alterations in inflammatory cytokines leading to suppression of antitumor immunity." (PMID 22978440, 2012). "Insulin is a humeral growth factor for a variety of cancer cells in vitro, and a variety of therapies targeting the insulin-like growth factor receptor are undergoing evaluation as potential anti-cancer treatment." (PMID 22421948, 2012).
cancer (continued). "Nutrient availability, insulin and related growth factors regulate cell survival by activation of the serine/threonine kinase Akt, which is a master regulator of cell metabolism, survival, growth and cancer and frequently activated in HCC." (PMID 22792392, 2012). "The mitogenic, antiapoptotic, and proangiogenic properties of insulin have been suggested as an explanation of its implication in cancer progression; furthermore, insulin is able to stimulate the synthesis of IGF-1, which has multiple effects that have been linked to tumor growth and metastasis." (PMID 23226214, 2012). "Our molecular data explain glucose- and insulin-induced changes in a cancer cell and help to understand what might trigger tumor cell proliferation and migration in DM2 patients, too." (PMID 22554284, 2012). "Many of the genes annotated with these PR-binding sites are critical regulators of cell migration, metabolic processes, and biosynthetic processes (Yin P and Bulun SE, unpublished data), and affect pathways including ErbB and insulin signaling, as well as pathways in cancer." (PMID 22272226, 2012). "Of the genes with PR-binding sites common to both cell types, several KEGG pathways were overrepresented, including those of focal adhesion, regulation of actin cytoskeleton, neurotrophin signaling, ErbB signaling, various cancer pathways, and insulin signaling." (PMID 22272226, 2012). "At least two different explanations are conceivable: The insulin signaling cascade in the whole prostate could be altered long before cancer develops with a second hit being necessary to trigger cancer emerging." (PMID 23251408, 2012). "Thus, in cancer cells metformin inhibited insulin-stimulated mTOR activation and proliferation in an AMPK-dependent manner." (PMID 22421948, 2012). "Interestingly, in the only study in which glycated hemoglobin was identical across treatment groups throughout the trial (i.e., DIGAMI-2) was also the one which reported a higher cancer-related mortality in patients randomized to insulin." (PMID 23209929, 2012). "Insulin promotes cancer cell growth, IGFs stimulate cell turnover in most body tissues." (PMID 22662119, 2012). "In fact, more recent studies demonstrated no or minimal increments in cancer risk and the data from insulin-treated patients are inconclusive." (PMID 22448244, 2012). "A recent study by the same investigators reevaluating the carcinogenicity potential of insulin glargine indicated that cancer risk was found to be no greater for animals treated with insulin glargine than for the control-treated animals." (PMID 23284776, 2012). "Randomized trials do not confirm the increased risk associated with insulin therapy, although they do not allow to rule out some negative effects on specific forms of cancer, at least at higher doses." (PMID 23209929, 2012). "In the majority of available surveys, insulin therapy was actually associated with significantly increased risk of cancer or a nonsignificant trend toward an increased incidence of malignancies." (PMID 23209929, 2012). "Insulin glargine use was associated with a lower odds of cancer compared with non-glargine insulin use (OR 0.81, 95% CI 0.68 to 0.98, P = 0.03; very low-quality evidence)." (PMID 23284776, 2012). "For many types of cancer, alterations in the insulin signaling cascade have been reported." (PMID 23251408, 2012). "In the UKPDS, the cumulative incidence of cancer-related death over 11 years similar in insulin-treated patients was similar (4.9 versus 5.0%) to that observed in other treatment groups, which included metformin, sulfonylureas, and conventional nonintensified therapy." (PMID 23209929, 2012). "However, the clinical relevance of the pro-cancer effect of insulin in diabetic patients is still unclear." (PMID 22526616, 2012). "One observational study showing a relationship between level of circulating insulin and cancer has suggested that cancer growth may be influenced by the insulin-IGF-1 signaling axis." (PMID 22719752, 2012).
cancer (continued). "High insulin levels and the associated changes of the IGF-1 axis may be associated with cancer development." (PMID 22778714, 2012). "Glargine, a long-acting insulin analog, may have even higher cancer risks compared with human insulin." (PMID 22778714, 2012). "Insensitivity to insulin has been observed in patients with cancer cachexia and may contribute to the development of cachexia." (PMID 21970879, 2011). "KEGG Pathway analysis demonstrated that the phosphorylated proteins in the whole proteomic analysis were involved in 200 different pathways, including the insulin signaling pathway, pathways in cancer, and the mitogen-activated protein kinase (MAPK) signaling pathway." (PMID 21738781, 2011). "Since 1885, when Ernst Freund described signs of hyperglycemia in 70 out of 70 cancer patients, it has been repeatedly reported that glucose tolerance and insulin sensitivity are diminished in cancer patients even before signs of cachexia (weight loss) become evident." (PMID 22029671, 2011). "Undoubtedly, insulin (human, pork, beef, and analogues) per se does not cause cancer or atherosclerosis." (PMID 21668983, 2011). "This could imply that diabetic patients with high insulin might have a worse cancer-specific prognosis." (PMID 29090133, 2011). "In addition, the IF animals displayed improved insulin sensitivity, reduced cancers and increased resistance of neurons and cardiac cells to oxidative and metabolic stress." (PMID 21385360, 2011). "In addition to having a role in cancer, proanthocyanidins have known health beneficial effects related to lipid and glucose metabolism, insulin signaling, oxidative stress and inflammation." (PMID 21998738, 2011). "Since insulin, glycemia, adiposity, and inflammation can be modified by antidiabetes pharmacotherapy, a better understanding of their pathophysiologic links to cancer may allow us to more effectively target DM2 treatment." (PMID 21773024, 2011). "A number of studies have examined the effect of exogenous insulin usage with cancer." (PMID 21773024, 2011). "In current clinical trials, the main IGF/INS target for cancer therapy is IGF1R." (PMID 20924377, 2010). "However, the development of NPC-derived cancer raises serious doubts about the safety of using adult stem cells in combination with insulin-producing cells outside the original microenvironment." (PMID 20436918, 2010). "Cancer mortality over follow-up was 4.9% (162 of 3,340) for sulfonylurea monotherapy users, and 3.5 (245 of 6,969) for metformin users (p = 0.01 for χ2 test) and 5.8 (84 of 1,443) for patients who used insulin." (PMID 21084729, 2010). "However, stable graft function was accompanied by constant and reproducible development of NPC-derived cancer which was sustained by insulin secretion." (PMID 20436918, 2010). "Type 2 diabetic patients in the present study showed both increased fasting insulin and serum HER-2 concentrations, two factors that may potentially increase cancer risk." (PMID 20184722, 2010). "The greatest handicap is that the database has not been created specifically to study insulin as a cause of cancer, or indeed, cancer as an outcome." (PMID 22276024, 2009). "However, there are a number of issues, some essential and some desirable, specific to the study of insulin and cancer, which must be taken into consideration." (PMID 22276024, 2009). "There is no basis at present for an effect of glargine insulin acting as a risk factor for the development of cancer." (PMID 24966880, 2009). "The hypothesis generated by the German study was that “the cancer incidence with glargine was higher than expected compared with human insulin”." (PMID 24966880, 2009). "Although not without controversy, the preponderance of studies suggest that insulin may influence cancers that are more commonly seen in Western population." (PMID 18665244, 2008).
cancer (continued). "Finally, GSCs share several features with most types of cancer cells, including sustained proliferation, the rate of which is sensitive to insulin signaling levels." (PMID 17150096, 2006). "Insulin-based therapies are generally ineffective in this setting and may worsen cancer outcomes." (PMID 42022705, 2026). "However, the ORIGIN trial did not report an increased risk of cancer among diabetic patients using exogenous basal insulin ‘glargine’ (hazard ratio: 1.00)." (PMID 40735043, 2025). "Thus, toxicogenomics data indicate that growth and insulin signaling, as well as cancer-related pathways may be sensitive to perturbations by these longer-chained PFAS." (PMID 40559910, 2025). "In addition, RPTOR (Regulatory Associated Protein Of mTOR Complex 1) has been reported to play a key role in nutrient and insulin-sensing pathways regulating cell growth in cancer, while SLC43A2 has also been identified as a regulator of the mTORC1 complex in cancer studies." (PMID 41373473, 2025). "Furthermore, higher CRF is often associated with decreased adiposity, which may indirectly reduce the incidence of cancer through its beneficial effects on insulin sensitivity." (PMID 41286400, 2025). "Patients on anti-cancer treatment who develop high blood glucose levels should be regularly monitored for levels of insulin and C-peptide, pancreatic amylase/lipase, anti-islet cell autoantibodies, anti-glutamic acid decarboxylase autoantibodies, anti-insulin antibodies and urine/capillary ketones." (PMID 40735043, 2025). "Further hypotheses and observations on the tumour microenvironment and CNAs could be generated by comparison of the insulin-expressing cancer cells to the single cell transcriptome of healthy primary canine beta cells, but such data are not available at present." (PMID 40438247, 2025). "The ketogenic diet may target cancer’s metabolic vulnerability, particularly in glioma and other metabolically dysregulated cancers, by lowering glucose and insulin, reducing inflammation and oxidative stress, and enhancing tumor response to standard therapies." (PMID 40959698, 2025). "This positions serum insulin as a key metabolic marker that may help predict cancer risk in individuals with or without underlying metabolic dysfunction." (PMID 41367907, 2025). "In addition, insulin exhibits a mitogenic impact on the processes involved in carcinogenesis and may favor cancer development through IGF-1." (PMID 38785834, 2024). "Furthermore, mechanistic evidence stems from the benefit of the ketogenic diet (essentially a low-carbohydrate diet) as an adjuvant therapy for several types of cancer, which in theory results in lower insulin levels and potentially reduces the insulin mitogenic effect." (PMID 39050345, 2024). "Indeed, there is increased production of growth factors, like insulin and insulin-like growth factor 1 (IGF-1), which promote cell growth and division and higher levels of sex hormones, particularly estrogen, which can influence cancer risk." (PMID 38541801, 2024). "Therefore, whole-body improvements in insulin signaling by metformin may contribute to cancer prevention mechanisms and mitigate cancer progression." (PMID 38543182, 2024). "Therefore, this suggests that the impact of metformin as an insulin sensitizer may be reversed in cancer cell microenvironments, inhibiting the growth-promoting efficacy of insulin in this context." (PMID 39267853, 2024).
cancer (continued). "Patients with cancer can present with normal to low glycemia (and consequently low fasting insulin) due to tumor hypermetabolism, concealing metabolic dysregulation; it is therefore valuable to measure glycemia, ketonemia, and insulin secretion during the feeding period (e.g., before dinner)." (PMID 39639257, 2024). "Due to this limitation, we could not analyze or discuss association of insulin dosage on cancer risk in our study." (PMID 39434861, 2024). "During a 5.4-year follow-up period, cancer-related mortality was 4.9% among SU users, 5.8% among insulin users, and 3.5% among metformin users, suggesting that metformin may offer protective effects against cancer, while insulin-promoting therapies may elevate oncogenic risk." (PMID 39595655, 2024). "Metformin may also exhibit anti-cancer activity by reducing circulating glucose and insulin levels." (PMID 37344841, 2023). "Additionally, patients with cancer had a higher risk of insulin requirement than patients without cancer (adjusted HR 1.43, 95% confidence interval [CI], 1.14–1.78)." (PMID 36831436, 2023). "In addition, insulin is regarded as a promoting factor in cancer development in some studies." (PMID 37185411, 2023). "Additionally, propranolol or closely related medications may still be able to lower blood sugar levels via the pancreas or improve insulin sensitivity even in cases where cancer cells exhibit the Warburg effect but lack adrenoceptors." (PMID 37051193, 2023). "Notably, a higher dietary proportion of sugar could result in high glucose levels and promote high insulin levels in parallel, leading to cancer growth." (PMID 37299548, 2023). "One of the most important signaling pathways in response to insulin signals, PI3K/Akt/mTOR, plays a crucial role in regulating malignant phenotypes such as cell proliferation, differentiation, invasion, and migration and is closely associated with the occurrence and development of malignant tumors." (PMID 38053170, 2023). "We show fasting’s ability to increase CBIs’ antitumour effects to depend on the reduction in circulating insulin, insulin-like growth factor-1 and leptin, which blunts the expression of enzymes from the cholesterol biosynthesis pathway and enhances cholesterol efflux from cancer cells." (PMID 37907500, 2023). "Interestingly, short‐term insulin use was found to be associated with increased risk of cancer but not for a longer duration use." (PMID 37148547, 2023). "Also, the exposure of cancer cells to high insulin levels stimulates mitogenesis." (PMID 34687971, 2022). "Whether insulin is related to various cancer types has attracted the attention of many researchers." (PMID 35256755, 2022). "However, some previous large randomized controlled trial study, cohort study, and systematic review concluded that insulin (analog) treatment does not impact the risk of cancer overall and some site-specific cancers." (PMID 35222270, 2022). "No increased risk of cancer with glargine vs. insulin NPH was seen." (PMID 35158824, 2022). "Moreover, KEGG assays indicated that RIPK4 expression may be associated with focal adhesion, proteoglycans in cancer, central carbon metabolism in cancer, and insulin secretion." (PMID 35310605, 2022). "Based on these results, patients who presented with IDacT were likely to have a high level of serum insulin that could promote disease development, and the residual cancer cells may become refractory to chemotherapeutic drugs due to the delayed administration of the next cycle of treatment." (PMID 35715761, 2022). "Among 6 up-regulated cancer driver genes, 4 genes encode proteins known to function as negative regulators of cell proliferation (CDKN2A); inducers of apoptosis (BAX); tumor suppressor (RPL22); inhibitors of transactivation of insulin promoter by recruiting a repressor complex (SPOP)." (PMID 36879662, 2022).